CXCL5 (C-X-C motif chemokine ligand 5)
Diseases named in the same sentence as CXCL5 in open-access papers (continued):
Sharing a sentence is not in itself a finding about the gene and the disease.
neuroblastoma (2 papers, 2016 to 2022). Neuroblastoma (NB) is the most common solid, extracranial childhood tumor. "The gene LOC101103238 (recently named CXCL5) and follistatin (FST) have been shown to be upregulated in mice inoculated with 22L prions prior to the development of clinical signs and in prion susceptible neuroblastoma cells, correspondingly." (PMID 26807844, 2016).
neurosyphilis (2 papers, 2016 to 2026). Infection of the brain or spinal cord by Treponema pallidum. "CSF CCL20, CCL15 and CXCL5 levels were down-regulated in neurosyphilis patients compared to those of non-neurosyphilis patients (with at least a 0.65-fold decrease, p < 0.05)." (PMID 27650493, 2016).
oral cancer (2 papers, 2023). "Correspondingly, IL-8 and CXCL5 were significantly upregulated in CAFs activated through oral cancer cell EVs (from Cal 27, SCC-9, and SCC-25 cells) according to differential expression analysis of RNA sequencing data." (PMID 37745296, 2023).
papillary thyroid carcinoma (2 papers, 2021 to 2022). "In papillary thyroid carcinoma cells, the CXCL5/CXCR2 axis was found to enhance mesenchymal marker vimentin and snail expression, thus promoting EMT of the tumor cells." (PMID 36612163, 2022). "Similarly, the addition of recombinant CXCL5 to papillary thyroid carcinoma cells downregulated epithelial cell markers and upregulated mesenchymal markers through activating β-catenin signaling." (PMID 36612163, 2022). "It is well established that the CXCL5/CXCR2 and IL-8/CXCR1/CXCR2 axes contribute to carcinogenesis by promoting tumor cell proliferation, migration, and invasion, and the EMT process of many tumor cells, including NSCLC, hepatocarcinoma cells, and papillary thyroid carcinoma cells." (PMID 34822613, 2021).
penile cancer (2 papers, 2021 to 2023). A primary or metastatic malignant neoplasm that affects the penis. "In penile cancer, preoperative serum levels of CXCL5 have been significantly linked with oncological variables such as T stage and nodal status, while survival analysis has shown a shorter disease-free survival (DFS) of patients with high serum CXCL5 levels." (PMID 36614308, 2023). "In conclusion, our findings revealed that serum CXCL5 level might serve as a potential diagnostic and prognostic cancer biomarker for penile cancer." (PMID 33458757, 2021). "Experimental therapeutics on CXCL5/CXCR2 inhibitors would be the priority of future studies in penile cancer." (PMID 33458757, 2021).
prostate adenocarcinoma (2 papers, 2019 to 2022). "For example, active YAP in murine prostate adenocarcinoma promotes CXCL5 (C-X-C motif chemokine ligand 5) secretion, which attracts CXCR2 (C-X-C motif chemokine receptor 2)-expressing myeloid derived suppressor cells (MDSC) to suppress the immune responses." (PMID 31052239, 2019). "WISP1v1 induced IL-6 and CXCL5 in vivo, suggesting that WISP1v1 might be involved in the pro-inflammatory environment of prostate adenocarcinoma in vivo." (PMID 36232736, 2022).
stomach adenocarcinoma (2 papers, 2020 to 2023). "Similarly, in stomach adenocarcinoma, CXCL5 has been shown to induce EMT in tumor cells according to an available in vitro study." (PMID 37686093, 2023).
systemic sclerosis (2 papers, 2018). A chronic disorder, possibly autoimmune, marked by excessive production of collagen which results in hardening and thickening of body tissues. "In contrast to ERG, the function of FLI1 is less-characterized in ECs; its ablation results in upregulation of CTSL and CXCL6 and downregulation of CXCL5 and CCN1 in the context of systemic sclerosis." (PMID 30500808, 2018).
abortion (1 paper, 2020). the ending of pregnancy by removing a fetus or embryo before it can survive outside the uterus. "Although abortion rates were not significantly different among the aging control and the signal suppression groups, birth rates were increased when CXCL5 signal was suppressed." (PMID 32959976, 2020). "Although abortion rates were not significantly different between controls and CXCL5‐treated group, birth rates of the embryos cultured with CXCL5 were significantly decreased as compared to controls (p < 0.05)." (PMID 32959976, 2020). "Both abortion and birth rates were also not influenced by CXCL5 signal suppression." (PMID 32959976, 2020).
anemia (1 paper, 2024). A reduction in the number of red blood cells, the amount of hemoglobin, and/or the volume of packed red blood cells. "Blood gas analysis showed dilutional anemia during V-V ECMO, whereas plasma analysis revealed a decreased concentration of IL-10 during V-V ECMO therapy, and BAL measurements showed increased concentrations of TNF-α, CXCL2, and CXCL5." (PMID 38928327, 2024).
biliary tract cancer (1 paper, 2021). "CXCL5 has been found to be involved in tumor progression in numerous types of cancers and could serve as a potential serum biomarker in various malignancies, including breast, nasopharyngeal, gastric, colorectal, and biliary tract cancer." (PMID 33458757, 2021).
bladder tumors (1 paper, 2022). "Comparison of chemoattractants expression during MB49 bladder tumors grow highlighted CCL8 and CCL12 (CCR2-ligands), CCL9 and CCL6 (CCR-1-ligands), CXCL2 and CXCL5 (CXCR2-ligands), CXCL12 (CXCR4-ligand) and antagonist of C5/C5a as potential targets to decrease myeloid suppressive cells." (PMID 36613562, 2022).
bone metastasis (1 paper, 2025). Transfer of a neoplasm from its primary site to bones. "We suspect that CXCL5 regulation could be related to the PC-3 origin from a bone metastasis." (PMID 40001606, 2025).
bone tumors (1 paper, 2019). "This study suggests that CXCL5 and CXCR2 inhibitors are attractive therapeutic targets that may have efficacy in treating or inhibiting the formation of metastatic bone tumors that are dependent on the CXCL5/CXCR2 signaling axis and resistant to current therapies." (PMID 31562303, 2019).
bronchopulmonary dysplasia (1 paper, 2016). Bronchopulmonary dysplasia is a chronic respiratory disease that results from complications related to lung injury during the treatment of infant acute respiratory distress syndrome in low-birth-weight premature infants or from abnormal lung development in older infants. "In addition, preterm infants with moderate or severe bronchopulmonary dysplasia had significantly higher CXCL5 levels in the gastric fluid than those with no or mild bronchopulmonary dysplasia did." (PMID 26738635, 2016).
cerebral palsy (1 paper, 2016). A group of disorders affecting the development of movement and posture, often accompanied by disturbances of sensation, perception, cognition, and behavior. "Our study findings suggest that CXCL5 may be a potential biomarker for white matter injury and cerebral palsy in preterm infants." (PMID 26738635, 2016).
cerebral small vessel disease (1 paper, 2022). Cerebral small vessel disease is the term currently used to pathological processes that affect the brain parenchymal circulation (arterioles, capillaries, and veins). "With a working model suggesting that DIO drives white matter endothelial CXCL5 expression through IL-17B/IL-17Rb signaling, we sought to establish the relevance of this signaling cascade to human cerebral small vessel disease and vascular cognitive impairment." (PMID 36543124, 2022). "Finally, we extend these findings to the human condition by demonstrating that CXCL5 is present in aged cerebral small vessels and that circulating levels of CXCL5 can identify subjects with imaging or cognitive manifestations of cerebral small vessel disease." (PMID 36543124, 2022).
cervical squamous cell carcinoma (1 paper, 2023). A squamous cell carcinoma arising from the cervical epithelium. "In another example, cervical squamous cell carcinoma and endocervical adenocarcinoma exhibited a negative correlation between the expression of CXCL1, CXCL6, and CXCL8 and EMT, whereas the expression of CXCL3, CXCL5, and PPBP positively correlated with EMT." (PMID 37686093, 2023).
cholestasis (1 paper, 2024). Impairment of the bile flow caused by obstruction within the liver, or outside the liver in the bile duct system. "Therefore, we isolated the hepatocytes from normal mice and treated them with GCA or TCA in vitro clarify the producing of CXCL2 and CXCL5 in cholestasis liver." (PMID 38951890, 2024). "As cholestasis progresses, excessive primary bile acids that accumulate in the liver intoxicates hepatocytes, which lead to exacerbated release of chemokines, particularly CXCL2 and CXCL5." (PMID 38951890, 2024).
cholesteatoma (1 paper, 2021). A pathologic process characterized by the proliferation of keratinizing squamous epithelium resulting in the accumulation of keratin and cells in the middle ear and/or mastoid. "Upon LPS challenge, we could detect a significantly higher expression of IL-1α, IL-1β, IL-6 and IL-8 in stem cells and of TNF-a, GM-CSF and CXCL-5 in stem cells and fibroblasts derived from cholesteatoma." (PMID 33627146, 2021).
chronic lung infection (1 paper, 2020). "Th17 lineage cytokines (IL-17A, IL-17F, and IL-22) and chemokines (CXCL1, CXCL2, CXCL5, and CXCL8) are known to control chronic lung infection caused by mycobacteria." (PMID 33520738, 2020).
chronic nasopharyngitis (1 paper, 2018). "In the present study, we found that CXCL5 and CXCR2 were upregulated in NPC tissues compared with those in non-tumour tissues from patients with chronic nasopharyngitis." (PMID 29665837, 2018).
colon adenoma (1 paper, 2024). An adenoma that arises from the colon. "In CRC, CXCL5 is predominantly released by cancerous epithelial cells, and its expression in CRC tissues is higher than in colon adenomas." (PMID 39273011, 2024).
colorectal tumour (1 paper, 2011). "Tumour conditioned media obtained from cultured colorectal tumour explant tissue contained high levels of the chemokines CCL2, CXCL1, CXCL5 in addition to VEGF." (PMID 22125641, 2011).
cyst (1 paper, 2022). A sac-like closed membranous structure that may be empty or contain fluid or amorphous material. "The chemokine profile is different compared to trophozoites, the main up-regulated chemokines are the same, but CCL4, CCL4L2, CSF1, CCL5, CXCL5, and CX3CL1 are more highly up-regulated in the cyst interaction." (PMID 35573800, 2022).
cystitis (1 paper, 2009). Inflammation of the urinary bladder. "Although urine CXCL-5 has been found to be elevated in women with cystitis or urosepsis, it has not been examined in ASB." (PMID 20016852, 2009).
dementia (1 paper, 2019). Loss of intellectual abilities interfering with an individual's social and occupational functions. "Our study highlights the changes and potential contributions of several chemokines (CXCL1, CCL3, CXCL5, CXCL6, CCL3, CCL19), interleukins (IL8, IL6-RA, IL18-BP), and other immune markers (OSM, ALCAM, OPG, CHIT1, YKL-40, STAMBP, MMP-9, MMP-10) in the prodromal and dementia phases of AD." (PMID 31694701, 2019).
diabetic foot ulcer (1 paper, 2023). "While the mechanistic role of CXCL5 in diabetic foot ulcer healing seems controversial, further systemic investigation was required." (PMID 37420254, 2023). "Given the potential role of CXCL5 in diabetic vasculopathy, future clinical study is indicated to elucidate if direct inhibition on systemic CXCL5 level may prevent the development of diabetic foot ulcer and improve wound healing in type 1 and type 2 diabetic patients." (PMID 37420254, 2023). "However, it was not known if reducing serum CXCL5 could promote the development of diabetic foot ulcer and retard wound healing." (PMID 37420254, 2023).
diabetic neuropathy (1 paper, 2015). A chronic, pathological complication associated with diabetes mellitus, where nerve damages are incurred due to diabetic microvascular injury involving small blood vessels that supply these nerves, resulting in peripheral and/or autonomic nerve dysfunction. "The results of our studies suggest an important role for CXCL1, CXCL5, CXCL9, and CXCL12 in STZ-induced diabetic neuropathy." (PMID 25789329, 2015). "This study verifies that, in streptozotocin-induced diabetic neuropathy, the spinal protein levels of CXCL1, CXCL5, CXCL9, and CXCL12, but not CXCL11 and CXCL13, are upregulated." (PMID 25789329, 2015).
endocrine cancers (1 paper, 2025). "Notably, endocrine cancers displayed the highest frequency of positive correlations with pro-inflammatory chemokine genes, particularly with CCL8, CCL11, CXCL1, CXCL5, and CXCL6, thus indicating a distinct regulatory pattern in this cancer subtype." (PMID 40806276, 2025).
endometrioid endometrial adenocarcinomas (1 paper, 2012). "CXCL5 is upregulated significantly in sporadic endometrioid endometrial adenocarcinomas compared to normal endometrium." (PMID 22950635, 2012).
Ewing sarcoma (1 paper, 2025). A small round cell tumor that lacks morphologic, immunohistochemical, and electron microscopic evidence of neuroectodermal differentiation. "In Ewing sarcoma, there were 21 significant relationships, including IL-4/IL-1β (r2 = 0.55, p = 0.00048), IL-4/IL-8 (r2 = 0.68, p = 0.0000047), CXCL14/IL-15 (r2 = 0.61, p = 0.00013), and CXCL5/CXCL12 (r2 = 0.64, p = 0.000030)." (PMID 41008853, 2025). "Patients with Ewing sarcoma showing high levels of CXCL10 had slightly better OS (p = 0.049), but IL-24 and CXCL5 levels had no prognostic significance." (PMID 41008853, 2025).
facial paralysis (1 paper, 2025). Severe or complete loss of facial muscle motor function. "This study also suggests that CXCL5 and SLAMF1 may act as common pathways of action between facial paralysis and IBD etiology, possibly through mechanisms that regulate immune responses, promote tissue repair, and maintain immune homeostasis." (PMID 40760834, 2025).
Fever (1 paper, 2023). Body temperature elevated above the normal range. "In our study, the chemokine Cxcl5 demonstrated significant increases in expression, signaling the onset of neutrophil granulocyte-driven local inflammation in the early stages of metal fume fever (MFF)." (PMID 38097754, 2023).
gastroduodenitis (1 paper, 2016). "Therefore, we suggest that neutrophil accumulation in tissue in children with gastroduodenitis is directed by a distinct set of chemokines including CXCL5 and CXCL6." (PMID 28018296, 2016). "In this study, we present novel data on the upregulation of CXCL5 and CXL6 in serum during gastroduodenitis." (PMID 28018296, 2016). "Here, we demonstrate upregulation of CXCL5 and CXCL6, potent chemoattractants for neutrophils in serum from juveniles with gastroduodenitis." (PMID 28018296, 2016). "Cytokines CXCL5 and CXCL6, potent neutrophil chemoattractants, were upregulated in all patients diagnosed with gastroduodenitis." (PMID 28018296, 2016).
Helicobacter infection (1 paper, 2017). "In order to characterize the inflammatory response across the infection, we analyzed the levels of IL-1β, IL-6, IFN-γ, CXCL5, and CXCL15, reported to be up-regulated upon Helicobacter infection in different studies." (PMID 29085807, 2017).
Hyperinsulinemia (1 paper, 2024). An increased concentration of insulin in the blood. "Long-term OZ treatment induced hypergastrin- and hyperinsulinemia and increased expression of Sirt1, Pparg, and Cxcl5 in mouse pancreatic tissues accompanied by specific changes in glucose metabolism." (PMID 38884019, 2024). "In conclusion, long-term OZ treatment induced hypergastrin- and hyperinsulinemia increased expression of Sirt1, Pparg, and Cxcl5 mRNA accompanied by specific changes in glucose metabolism." (PMID 38884019, 2024).
hypertensive retinopathy (1 paper, 2022). Retinopathy due to hypertension. "We evaluated the expression levels of a series of chemokines (CXCL1, CXCL2, CXCL3 and CXCL5) and their receptor CXCR2 in Ang II-treated retinas to investigate the role of chemokines and their receptors in hypertensive retinopathy." (PMID 35981418, 2022).
keratoconus (1 paper, 2023). A degenerative, structural disorder of the eye, characterized by a cone-shaped protrusion of the cornea. "Ultimately, it was found that the chemokine receptors CCR2 and CCR5, as well as F2RL1 and CXCL5, may be involved in the immune regulation process of keratoconus." (PMID 37965330, 2023).
kidney failure (1 paper, 2021). An acute or chronic condition that is characterized by the inability of the kidneys to adequately filter the blood. "The only advent of kidney failure, liver failure, and need for pressors was associated with elevation of specific markers (CCL4, CD40, CXCL5, and IL-15), but our findings’ interpretation needs more broad context." (PMID 34177897, 2021).
Klebsiella pneumoniae pneumonia (1 paper, 2015). "Jeyaseelan and colleagues reported that CXCL1 regulates expression of CXCL2 and CXCL5 during murine Klebsiella pneumoniae pneumonia." (PMID 25621893, 2015).
liver cirrhosis (1 paper, 2021). "The relative mRNA expression of CXCL5 of HCC patients were higher than patients with liver cirrhosis, patients with Chronic HBV infection, also the ELISA detected results of CXCL5 of HCC patients were higher than patients with liver cirrhosis, patients with Chronic HBV infection." (PMID 33869023, 2021).
macrophage activation syndrome (1 paper, 2021). A complication of rheumatic disease that is caused by excessive activation and uncontrolled proliferation of T lymphocytes and well-differentiated macrophages. "Further studies are needed to elucidate the role of neutrophils in the initiation of a macrophage-activation syndrome (MAS)-like condition in mice infected with SARS-CoV-2, as well as the importance of CXCL5 in influencing the outcome of infection." (PMID 34835277, 2021).
malignant rhabdoid tumors (1 paper, 2021). "Using this method, CXCL5/CXCL6 genes were recognized to be overexpressed in malignant rhabdoid tumors." (PMID 33673696, 2021).
malnutrition (1 paper, 2021). Inadequate nutrition resulting from poor diet, malabsorption, or abnormal nutrient distribution. "Increased levels of duodenal IL-17A, IL-21, IL-22, CXCL5 due to malnutrition—together with decreased levels of TNFα, IL-12, TGFβ and CXCL10 and elevated levels of IgA due to infection—revealed that the duodenum was sensitive to both variables and suggested local inflammation in malnourished animals." (PMID 34207946, 2021).
memory impairment (1 paper, 2021). "We sought to investigate that the roles of CRHR1 and CXCL5 in learning and memory impairment caused by prenatal sGC exposure." (PMID 33810797, 2021).
Meniere disease (1 paper, 2025). A disease of the inner ear (labyrinth) that is characterized by fluctuating sensorineural hearing loss; tinnitus; episodic vertigo; and aural fullness. "ENA-78 (CXCL5): Preliminary studies suggest that levels of ENA-78 might be lower in the peripheral blood mononuclear cells of Meniere’s disease patients compared to those with vestibular migraine." (PMID 41306961, 2025).
metastatic cancer (1 paper, 2019). A carcinoma which has spread from the original site of growth to another anatomic site. "Additional studies using CXCL5 recombinant protein suggest that CXCL5 is sufficient to promote breast cancer cell proliferation and colonization in bone, while inhibition of its receptor CXCR2 with an antagonist blocks proliferation of metastatic cancer cells." (PMID 31562303, 2019).
MRSA pneumonia (1 paper, 2022). "MRSA pneumonia was associated with high concentrations in BALF of proinflammatory cytokines (TNF-α, IL-6) and chemokines (CXCL2, CXCL5)." (PMID 35972289, 2022).
mucositis (1 paper, 2017). Mucositis is inflammation and damage of the mucous membranes lining the mouth and other parts of the gastrointestinal (GI) tract. "So far the role of CXCL5 in 5-Fu induced mucositis has not been elucidated yet." (PMID 29124041, 2017).